BAP1 (BRCA1 associated deubiquitinase 1)
Diseases named in the same sentence as BAP1 in open-access papers (continued):
Sharing a sentence is not in itself a finding about the gene and the disease.
meningioma (continued). "Benign lesions associated with the BAP1 mutation include multiple cutaneous melanocytic neoplasms called “BAP1-inactivated melanocytic tumors” and meningiomas." (PMID 37239385, 2023). "Many BAP1-mutant meningiomas have overt rhabdoid cytomorphology, but the histology can be diverse, including epithelioid-type cells and papillary growth." (PMID 35969220, 2022). "Regardless, we present the first report of a familial BAP1 inactivation TPDS identified after multiple generations of a family presented with meningioma with rhabdoid features instead of presenting with malignancies." (PMID 34504799, 2021). "Neither tumor contained mutations in additional genes associated with meningioma (such as NF2 and AKT1) or malignancy, strongly implicating BAP1 inactivation in disease pathogenesis." (PMID 34504799, 2021). "Recently, inactivating BAP1 mutations have been linked to significantly reduced time to recurrence in both Grade III rhabdoid and lower grade meningioma with rhabdoid features (26 months versus 116 months, p < 0.001, hazard ratio 12.89)." (PMID 34504799, 2021). "The frequency of NMSC was substantially higher compared to meningioma and cholangiocarcinoma, with 19 affected BAP1-TPDS patients (19/72, 26%)." (PMID 31382694, 2019). "Of note, BAP1 expression has been reported to be lost in several cancer types, including a subset of clinically aggressive meningiomas that display a rhabdoid or papillary histology, in association with both a higher tumor grade and a significantly decreased time to recurrence." (PMID 38785832, 2024). "Although BAP1 inactivation has been reported in patients with high-grade RM carrying germline mutations, indicating that such meningiomas can arise as part of the BAP1-TPDS, in other RM cases BAP1 inactivation might be caused by somatic BAP1 loss." (PMID 38785832, 2024). "Mutations in SMARCE1, BAP1, KLF4/TRAF7, TERT promoter, and CDKN2A/B deletion, H3K27me3 loss and methylation profiling are now officially associated with the classification and grading of meningiomas." (PMID 34846640, 2022). "Otherwise, mutation of SMARCE1 or BAP1, can rarely be found in WHO grade 2 or 3 meningiomas." (PMID 35892898, 2022). "BAP1-TPDS individuals may also develop meningiomas, which are primary central nervous system (CNS) tumors of the meninges." (PMID 35885614, 2022). "Despite not meeting the full criteria for Grade III rhabdoid meningioma, both patients’ meningioma with rhabdoid features in our study displayed biallelic BAP1 inactivation via an inherited germline BAP1 (p.Gln593*) mutation and biallelic inactivation by different somatic mechanisms." (PMID 34504799, 2021). "Further, 1.7% of patients with BAP1 TPDS develop meningiomas." (PMID 33801089, 2021). "Shankar reported in a series of 14 meningiomas with rhabdoid features, that loss of BAP1 resulted in decreased progression free survival compared to those tumors without BAP1 mutations." (PMID 33346248, 2020). "However, until now there are no clinical studies linking BAP1-mutated meningiomas with distant extracranial metastasis." (PMID 36641486, 2023). "In addition, the tumor suppressor gene BAP1 is another biomarker for aggressive meningioma and may also represent a potential therapeutic target because BAP1 inactivation may increase tumor sensitivity to PARP inhibition." (PMID 36005176, 2022). "Interestingly, we observed loss of BAP1 expression in the nucleus and in cytosol of meningioma cells as well as in BCC cells from two different germline BAP1 PV carriers belonging to two different families, confirming that meningioma and BCC are also included in the broader BAP1-TPDS spectrum." (PMID 35885614, 2022). "RESULTS: In a cohort of 237 subjects with BAP1-TPDS, we identified 6.8% (16/237) with a history of meningiomas." (PMID 41670784, 2026).
meningioma (continued). "Prior retrospective analyses and case series have discovered familial BAP1 TPDS after patients presented with these malignancies, and in some cases, close relatives were later found to have meningiomas." (PMID 34504799, 2021). "Within the group of aggressive meningiomas lacking NF2 mutation, in approximately 5% of tumors alterations in chromatin regulators BAP1 and PBRM1 were encountered and correlate with a more aggressive clinical behavior." (PMID 36641486, 2023). "In our case, however, more than 80% of the samples that acquired 3p-loss (that overlapped BAP1 and PBRM1) without 22q-loss were grade I, extending a role for this driver to a broader spectrum of meningiomas that includes low grade lesions." (PMID 37805627, 2023). "Interestingly, most cases with sequence alterations in BAP1, CDKN2A/B, and TERT occurred in meningiomas with a low-grade cytogenetic background." (PMID 35299730, 2022). "These cases demonstrate the importance of routine BAP1 tumor testing in meningioma with rhabdoid features regardless of grade, germline testing for patients with BAP1 inactivated tumors, and tailored cancer screening in this population." (PMID 34504799, 2021). "At this time, BAP1 inactivation is not routinely tested for in rhabdoid meningioma let alone meningioma with rhabdoid features." (PMID 34504799, 2021). "In addition, 81% of BAP1 and 87.5% PBRM1 mutant meningiomas were classified as WHO grades 2 and 3 meningiomas." (PMID 33087175, 2020). "Furthermore, several typical meningioma locations have distinct related genomic markers (e.g., anterior skull base: SMO, AKT1E17K, TRAF7; central skull base: AKT1, KLF4, TRAF7, POLR2A, Convexity: NF-2, LOH chromosome 22, BAP1)." (PMID 38017560, 2023). "Interestingly, none of the other meningioma subtypes with characteristic alterations, e.g. mutations in NF2, TRAF7/KLF4 or BAP1, or YAP1 fusion, seem to form epigenetic clusters that are distinct to the same extent." (PMID 33319313, 2021). "Meningiomas with rhabdoid histopathologic features appear to encompass a diverse genetic spectrum, and BAP1 function may be just as important, if not more so, than morphology." (PMID 34504799, 2021). "BAP1 mutant meningiomas localize to cerebral convexities, while SMO mutant meningiomas are located in the anterior skull base, but not midline." (PMID 36033542, 2022).
cholangiocarcinoma (48 papers, 2014 to 2026). A carcinoma that arises from the intrahepatic biliary tree (intrahepatic cholangiocarcinoma) or from the junction, or adjacent to the junction, of the right and left hepatic ducts (hilar cholangiocarcinoma). "BRCA1-associated protein 1 (BAP1) is a deubiquitinase, frequently altered in cancers including hepatocellular carcinoma and cholangiocarcinoma." (PMID 41712409, 2026). "Somatic BAP1 mutations have also been identified in other malignancies, including cholangiocarcinoma and thymic cancers." (PMID 37607989, 2023). "We conclude that, in contrast to intrahepatic cholangiocarcinoma, loss of expression of BAP1 occurs very rarely in pancreatic ductal adenocarcinoma." (PMID 26982343, 2016). "Loss of BRCA associated protein-1 (BAP1) expression has been found in up to a quarter of intrahepatic cholangiocarcinomas." (PMID 26982343, 2016). "Likewise, cholangiocarcinoma has been investigated due to the high somatic mutation rate in BAP1 in these tumours." (PMID 37607989, 2023). "Other malignancies often reported in carriers of germline BAP1 mutations include most types of skin cancers, breast cancer, cholangiocarcinoma, non-small cell lung adenocarcinoma, meningioma, sarcomas, peripheral nerve sheath tumor, and neuroendocrine carcinoma." (PMID 30001711, 2018). "We previously demonstrated that BAP1 loss characterized a cholangiocarcinoma-like (CHOL-like) expression-based subset of liver hepatocellular carcinomas and hypothesized that CHOL-like liver tumors represented BAP1-driven changes resembling a transdifferentiated cell phenotype." (PMID 39554490, 2024). "When introducing other known liver cancer (cholangiocarcinoma) gene mutations in the organoids in combination with the BAP1 mutation, the authors could show that BAP1 loss-of-function is required for tumourigenesis when mutant organoids are transplanted into mice." (PMID 33057820, 2021). "Genetic alterations in chromatin modulators such as BRCA-1 associated protein-1 (BAP1) are the most frequent genetic alteration in intrahepatic cholangiocarcinomas (CCA)." (PMID 28122578, 2017). "Consistent results were obtained in the high-throughput drug synergy screen of the cholangiocarcinoma cell line TFK-1, with stronger synergism upon BAP1 loss." (PMID 40754831, 2025). "While the CCA-like histologically resembles HCC, molecularly, they look more like cholangiocarcinomas with similar patterns of DNA mutations (IDH1/2, BAP1), DNA damage repair mutational signatures, and transcriptional patterns." (PMID 36077818, 2022). "Although cholangiocarcinoma has been reported as a less common manifestation of BAP1‐TPDS, the family history in our case was limited to bile duct cancer in the paternal grandfather and gastric cancer in the maternal grandfather, without a history of core BAP1‐associated tumours." (PMID 40979255, 2025). "Additionally, the subset of CHOL-like hepatocellular carcinomas had lower BAP1 activity scores and were phenotypically more similar to cholangiocarcinomas than to other hepatocellular carcinoma samples." (PMID 39554490, 2024). "BAP1 has been shown to be frequently inactivated in cholangiocarcinomas." (PMID 35581624, 2022). "Somatic loss of BAP1 was due to different mutations in PlM of the right thoracic cavity, peritoneal mesothelioma, lung adenocarcinoma, and bladder cancer, whereas no BAP1 somatic mutation was observed in cholangiocarcinoma and PlM of the left thoracic cavity." (PMID 35885614, 2022). "The first patient (germline BAP1 p.K453Rfs*) underwent a radical nephrectomy at 46 years of age for 2 synchronous clear cell RCCs and subsequently developed epithelioid mesothelioma and cholangiocarcinoma." (PMID 34767027, 2021). "In cholangiocarcinoma, low BAP1 status conferred greater sensitivity to gemcitabine." (PMID 30669483, 2019).
cholangiocarcinoma (continued). "A BAP1 dependent alteration in expression of lncRNA NEAT-1 was identified by RT-PCR based lncRNA expression profiling, and an inverse relationship between this lncRNA and BAP1 was observed in analysis of the Tumor Cancer Genome Atlas cholangiocarcinoma dataset." (PMID 28122578, 2017). "For example, BAP1 conversely regulated the expression of NEAT-1, which contributed to sensitivity to gemcitabine in cholangiocarcinoma." (PMID 29654165, 2018). "IDH mutation and FGFR rearrangement are usually specific to IHCC, whereas BAP1 and IDH mutations are more frequently detected in non-parasite related cholangiocarcinoma than in those related to parasite infection." (PMID 27136744, 2016). "Alterations in chromatin remodeling genes (ARID1A, BAP1, IDH1, IDH2, PBRM1, SMARCB1) were found in 30.7% (47/153) of cancers in our series, confirming recent reports on the significant involvement of these genes in cholangiocarcinoma." (PMID 24867389, 2014).
metastatic disease (45 papers, 2013 to 2025). "All UM samples originated from metastatic tumors, some of which harbored inactivating mutations in BAP1, an event that frequently occurs in metastatic tumors and correlates with poor prognosis." (PMID 38233483, 2024). "Mutations in SF3B1 have been correlated with an intermediate potential to develop metastatic disease, occurring later than BAP1 mutations, usually around 7 years after primary treatment." (PMID 39061150, 2024). "Because inactivating BAP1 mutations have emerged during the last years as prognostically relevant markers for metastatic disease, we looked for a potential correlation between histone PTMs and the BAP1 status." (PMID 38349785, 2024). "An inactivating mutation of BRCA1-associated protein 1 (BAP1) – a tumor suppressor gene – usually occurs in later stages and is highly associated with metastatic disease in UM." (PMID 38349785, 2024). "In contrast to the tissue samples, TS only identified mutations in GNA11 [variant allele frequency (vaf) = 0.92%] and BAP1 (vaf = 1.57%) at one plasma timepoint in 1 patient with metastatic disease 6 months after brachytherapy (Patient 09—6 months)." (PMID 36860651, 2023). "The literature shows that tumor size and factors as chromosome 3-loss and BAP1 mutation determine the risk of metastatic disease." (PMID 35922562, 2022). "It has been demonstrated that the genetic high-risk features, such as chromosome 8q gain and loss of BAP1, are frequent in patients with metastatic disease." (PMID 36338696, 2022). "The mutation of BAP1 was previously reported to be associated with the UM metastasis, but only 50% (13/26) of metastatic tumors presented with BAP1 mutation, whose incidence was also much lower than that of SLC25A38 downregulation." (PMID 35411037, 2022). "Specifically, mutations in the BRCA1-associated protein 1 (BAP1) are found only in NPC patients with metastatic disease." (PMID 36135044, 2022). "Only two patients demonstrated discordant BAP1 immunohistochemical expression, with the loss of BAP1 during the progression to metastatic disease." (PMID 34885018, 2021). "Although BAP1–located on chromosome 3–correlates well with the chromosome 3 status and a BAP1 mutation is associated with a high likelihood for metastatic disease, EIF1AX and SF3B1 occur typically in disomy 3 tumors." (PMID 34439147, 2021). "In contrast, CCRCCs with BAP1 mutations or multiple driver mutations are associated with aggressive clinical behavior and early metastatic disease." (PMID 34885018, 2021). "Among known risk factors for the development of metastatic disease is the loss of BAP1 expression and chromosome 3 monosomy in the primary tumor." (PMID 32131485, 2020). "The genetic high-risk features, such as monosomy 3 and BAP1 mutations, are more frequently seen in patients with metastatic disease." (PMID 32718045, 2020). "The tumour suppressor BAP1 gene shows inactivating mutations in 85% of aggressive tumours and is considered to be a marker of metastatic disease." (PMID 32299493, 2020). "Two had been classified as D3 by MLPA but M3 by NGS; one had a BAP1 mutation and both patients had died from metastatic disease." (PMID 32340176, 2020). "Inactivating somatic mutations in the BAP1 gene in UM were first identified and associated with metastatic disease in 2010." (PMID 30477459, 2018). "Both OM-091 and UM36 patients died of metastatic UM, consistent with previous studies linking BAP1 mutations in primary UM with a high likelihood of developing metastatic disease." (PMID 28594900, 2017). "We observed that loss of BAP1 protein expression was nearly 100% concordant between patient-matched primary and metastatic tumors." (PMID 28327121, 2017). "No patients with EIF1AX or SF3B1 mutations in this cohort are known to have developed metastatic disease with the exception of 2 patients that had co-occurring BAP1 mutations." (PMID 28594900, 2017).
metastatic disease (continued). "Related to this, Gerlinger and colleagues compared mutations from patient-matched primary and metastatic tumors in four patients; all four were BAP1 wild type and two had PBRM1 mutations." (PMID 28327121, 2017). "To date, monosomy 3 and mutated BAP1 have been associated with UM metastasis, but limited analyses of metastatic tumor genomes have been reported." (PMID 28594900, 2017). "Mutations in BAP1, a deubiquitinating enzyme located on chromosome 3p, are seen in 85% of high-risk (“class-2”) UMs and correlate with development of metastatic disease." (PMID 24403233, 2013). "A mutation in the BAP1 gene significantly increases the risk of metastatic disease." (PMID 39061150, 2024). "Furthermore, specific genetic features associated with metastatic disease include loss of chromosome 3 and mutations in the BAP1 (BRCA-associated protein 1) and SF3B1 (encoding splicing factor 3B subunit 1A) genes." (PMID 38175637, 2024). "When BAP1 is mutated, it causes a significant risk of metastatic disease in UM patients." (PMID 35309331, 2022). "BAP1 mutations are associated with early metastatic disease, although its underlying mechanism remains unclear." (PMID 35954332, 2022). "However, UM with somatic BAP1 mutations are correlated to loss of chromosome 3 and early metastatic disease." (PMID 34071371, 2021). "In addition to CTNNB1‐activating mutations, we found inactivating mutations of epigenetic regulators (KDM6A, TET1, BAP1) associated with metastatic disease." (PMID 30306561, 2019). "In fact, BAP1 mutations in tumors are associated with pathological features of aggressive disease including high Fuhrman grade, metastatic disease at presentation, worse cancer specific survival, instantaneous activation of mTOR signaling, and activation of pathways implicated in growth factors." (PMID 28812986, 2017). "This is consistent with the MSKCC cohort study findings, where BAP1 mutations were associated with poor prognostic factors, such as a higher T stage, higher nuclear grade, larger tumor size, more necrosis, and the presence of metastatic disease at presentation." (PMID 40856833, 2025). "The cases presented in this report highlight the complexity of managing advanced ccRCC, especially when extensive metastatic disease and BAP1 alterations are present." (PMID 41561288, 2025). "BAP1 and SF3B1 mutations are found most frequently in metastatic disease, whereas EIF1AX gene mutation is related to a favorable prognosis." (PMID 38175637, 2024). "Three cases harbored alterations in BAP1 in both the primary and metastatic tumors (case #2, #3 and #4)." (PMID 36641486, 2023). "There are currently no medications available that target the YAP-TAZ pathway, which is also active in UM, the cancer-suppressor gene BAP1, or the SF3B1 gene, whose mutations increase the likelihood of metastatic disease." (PMID 37124608, 2023). "Comparing gene expression across patient-matched primary-metastatic tumor pairs, 98% had concordant BAP1 status." (PMID 34885018, 2021). "Another study, using an immunohistochemical assay, found inter-metastatic tumor heterogeneity of BAP1 in only 1 of 32 patients (3%)." (PMID 34885018, 2021). "In this study, the authors also examined intra-metastatic tumor heterogeneity, and found a 100% concordance in BAP1 between 12 patients." (PMID 34885018, 2021). "Comparing expression across patient-matched primary-metastatic tumor pairs, the authors reported that 98% had concordant BAP1 status (90% PBRM1)." (PMID 34885018, 2021). "Amongst 32 patients who had serial metastatic tumors available, both BAP1 and PBRM1 had 97% concordant expression." (PMID 28327121, 2017). "Lastly, we evaluated the concordance of loss of BAP1 and PBRM1 expression across patient-matched primary and metastatic tumors in a large cohort of ccRCC patients." (PMID 28327121, 2017). "Comparing expression across patient-matched primary-metastatic tumor pairs, 98 and 90% had concordant BAP1 and PBRM1 expression, respectively." (PMID 28327121, 2017).